CCL2 (C-C motif chemokine ligand 2)
Diseases named in the same sentence as CCL2 in open-access papers (continued):
Sharing a sentence is not in itself a finding about the gene and the disease.
tumor (continued). "Tumor and stroma cells secrete CCL2 to recruit inflammatory monocytes and TAMs expressing CCR2." (PMID 32471499, 2020). "It is shown that CCL2 expression is up-regulated by macrophages and tumor cells in TME." (PMID 33251232, 2020). "Since CCR2 is crucial for many types of leukocytes to be recruited into tumor microenvironment via CCL2, the high expression of Ccr2 mRNA observed in both TRAMP-C1 and LLC derived tumor tissues may reflect the enrichment of leukocytes." (PMID 32244522, 2020). "The inflammatory reaction was manifested by elevated levels of circulating myeloid cells (monocytes and neutrophils), and elevated expression of inflammatory mediators, including the major monocyte chemoattractant CCL2; CCL2 down-regulation has led to partial reduction in tumor outgrowth." (PMID 33585241, 2020). "Furthermore, they modulate pro-tumorigenic inflammation through secretion of IL-1, IL-6, TNF-α, TGF-β, and CCL2, favoring tumor growth, angiogenesis, invasion and metastasis." (PMID 32499779, 2020). "Thus, reduction of Ccl2 expression can decrease neutrophil-mediated killing of tumor cells and promote a protumorigenic microenvironment." (PMID 33330473, 2020). "Similarly, CCL2 that was released by senescent melanoma cells increased tumor cell invasion and CCL5 derived from age-senescent fibroblasts elevated the proliferation of prostate epithelial cells." (PMID 32582148, 2020). "For what concerns the mechanism of action, it was found that the same led to a reduction of microvessel density around the tumor mass (24–58%) and, although only at the concentration of 50 mg/kg, to a decrease (45%) of the release of chemokine (C-C motif) ligand 2 (CCL2)." (PMID 33327602, 2020). "The hypothesized mechanism of action of PF-04136309 is the inhibition of CCL2-induced trafficking of IM from the bone marrow to the tumor." (PMID 31297636, 2020). "Furthermore, it was reported that CCL2/CCR2 axis indirectly promotes tumor progression by increasing the recruitment and suppressive activity not only TAMs, but also MDSCs, the immunosuppressive cells of myeloid origin." (PMID 32456359, 2020). "In addition, studies on the role of CCL2 in cancer have been reported since 2000, and the role of CCL2 in the tumor microenvironment, immuno-oncology, and cancer cells has been the main topic of CCL2 research nowadays." (PMID 33297571, 2020). "The authors of this study hypothesized that tumor-derived-CCL2 is crucial for the recruitment of macrophages, which exert immunosuppressive effects." (PMID 33371444, 2020). "Accordingly, TAMs may be recruited via CCL2 to mediate bladder cancer metastasis through indirect crosstalk with tumor circRNAs." (PMID 32943996, 2020). "Finally, compared to macroH2A1 KD Huh-7 cells, FAK KD cells exhibited a significant reduction (p < 0.01) in the mRNA levels of tumor-promoting genes CCL2, EGF, BAX, KRT19, EGFR, NOTCH1, ABL1, and SMAD3." (PMID 33182805, 2020). "In addition, microglia from the GBM tumor microenvironment have the capacity to secrete CCL2, thereby stimulating more microglia recruitment to the tumor." (PMID 32765498, 2020). "In tumor-bearing mice, CCL2 expression is significantly increased in the blood and tumor tissues." (PMID 32000802, 2020). "Similarly, accelerated tumor progression was accompanied by an overall increase in macrophages and tumor cytokines, including CCL2, in a collagen-dense mammary tumor model compared to controls." (PMID 32509583, 2020). "The CCL2/CCR2 axis plays a vital role in the recruitment of TAMs to tumor tissues." (PMID 33224886, 2020).
tumor (continued). "Similarly, in mouse models of glioma, it has been demonstrated that treatment with COX-2 inhibitors reduces the PGE2 production which results in a decrease of MDSC-attracting chemokine CCL2 in the tumor." (PMID 33271839, 2020). "Importantly, MSCs possess several surface markers (e.g., CXCR4, CXCR12, and CCL2) that allow them to home to the tumor sites in response to chemokines secreted by the tumor cells." (PMID 32295145, 2020). "Both CCL2 and CCL5 mediate the infiltration of tumour-associated macrophages and inhibit potential anti-tumour T-cell activities, thereby controlling the populations of leukocytes at tumour sites." (PMID 33046030, 2020). "Taking into account the previously shown correlation between the presence of monocytes and Ly6Clow macrophages, we first demonstrated that PH induces the expression of CCL2 (a chemoattractant for monocyte) and GM-CSF in the early hours following PH in tumor-free wild-type mice." (PMID 33178579, 2020). "Similarly, Monocyte chemoattractant protein- 1 (MCP-1) also known as CCL2 (C-C motif chemokine ligand 2), and its receptor CCR2 (C-C chemokine receptor type 2) were linked to tumor growth and poor prognosis in colon, breast, prostate, and cervical cancer." (PMID 32355198, 2020). "Several studies suggest that tumor cell-derived lncRNAs may also be involved in the secretion of factors such as CCL2, coagulation factor X (FX), and exosomal miRNAs to promote tumor metastasis by influencing macrophage recruitment and polarization." (PMID 32083005, 2020). "Also the Aryl Hydrocarbon Receptor (AHR) is indirectly implicated in recruiting monocytes to the tumor environment by driving CCR2 expression, the receptor for the major monocyte chemoattractants CCL2 and CCL7." (PMID 32014107, 2020). "Several studies have demonstrated a role of CCL2 in recruiting MDSCs to tumor sites." (PMID 32471499, 2020). "By binding CCR-2, CCL-2 promotes tumor growth and metastasis." (PMID 33228048, 2020). "However, it seems that CCL2 in a tumor interferes with the function of anti-cancer T lymphocytes and dendritic cells." (PMID 33182504, 2020). "Conversely, nitro-CCL2 recruits MDSCs supporting angiogenesis and tumor growth." (PMID 33262763, 2020). "Mechanistically, imperatorin can directly bind with CREB1 and inhibits its phosphorylation and interaction with TGFβ2 promoter, then inactivates extracellular signal‐regulated kinases (ERK) signaling and fibroblasts‐secreted CCL2 to block tumor angiogenesis and metastasis." (PMID 32832354, 2020). "Preclinical studies with CCL2 blocking antibodies or small molecule inhibitors supported the notion of their key role in the intratumor accumulation of TAMs, through signaling pathways that are strictly dependent on the tumor type." (PMID 32708142, 2020). "In addition to tumor cells, various cells in the host microenvironment, including infiltrating leukocytes, endothelial cells, and fibroblasts, as well as adipocytes, are able to produce cytokines/chemokines such as CCL2 for tumor growth and progression." (PMID 32471499, 2020). "Furthermore, tumor cells release colony-stimulating factor 1 (CSF-1), CCL2, and CCL5, promoting the recruitment of macrophages." (PMID 33371444, 2020). "In mouse models, preconditioning of the tumor microenvironment with small molecules blocking RNS production increased the CCL2-mediated recruitment of adoptively transferred tumor-specific CD8 T cells, making it an interesting target for further therapeutic development." (PMID 33013822, 2020). "CCL2 and CCL8 also cause enhanced tumor cell stemness and cancer stem cells self-renewal." (PMID 33182504, 2020). "Among all these, tumor-derived CCL2 stimulates the accumulation of myeloid cells and controls the differentiation of MDSCs into immunosuppressive macrophages, which in turn enhance metastases formation (e.g., CSCs establishment, proliferation and differentiation)." (PMID 32397392, 2020).
tumor (continued). "This could be due to a number of factors, including decreased CCL2 signaling (limiting metastatic nice formation), along with changes in tumor cell adhesion." (PMID 32455980, 2020). "Indeed, we demonstrated anti-inflammatory status as evidenced by reduced Ccl2 and Cxcl1 in all the tumor tissues compared to the primary cells." (PMID 32244522, 2020). "Together, these results suggest that chronic inflammation induced by CCL2 significantly enhances tumor growth and promotes the formation of a desmoplastic stroma through early recruitment of macrophages and fibrocytes into the tumor microenvironment." (PMID 32731354, 2020). "Macrophages can be recruited to hypoxic region of tumor by CCL-2, where upregulated HIF1α/HIF2α orchestrates the transcription of many angiogenesis related genes including VEGF, CXCR4, CCL2, and endothelins which reciprocally enhanced the recruitment of macrophage." (PMID 33343560, 2020). "CCL2 recruits more macrophages into the tumor to promote lymphatic metastasis via VEGF-C secretion." (PMID 33178603, 2020). "Cytokines released from tumor-residing cells including tumor cell–derived IL-4, IL-10, CCL2, CCL3, CCL4, and CSF1; Treg-derived IL-10; B cell–produced immunoglobulins; Th2-derived IL-4 and IL-13; and MSC-derived MFG-E8 promote the polarization into a protumor phenotype." (PMID 31256327, 2020). "Similarly, in breast cancer metastasis models, monocytes (recruited to DTCs by CCL2 produced in the lung both by the tumor and the surrounding stroma) differentiate into MAMs that promote DTC proliferation." (PMID 33022920, 2020). "Furthermore, CCL2 was originally identified as a tumor-derived chemotactic factor for macrophages, and the levels of tumor-derived CCL2 significantly correlate with macrophage density and the depth of invasion in various cancers." (PMID 33330033, 2020). "In turn, the production of CCL2 by tumor cells was enhanced that promoted macrophage recruitment." (PMID 33194645, 2020). "However, 70% of myeloid cells infiltrate the tumor tissue independently of the CCR2/CCL2 signaling axis." (PMID 32668709, 2020). "Paralleling previous reports, our study demonstrated that CCL2 acts to bridge tumor cells with TAMs-associated immune response rather than directly impact ESCC markers in the tissue microenvironment during esophageal carcinogenesis." (PMID 32103760, 2020). "The aim of our study was to analyze for the first time the expression of CCL2 in BCa tumor cells and immune cells by immunohistochemistry and to correlate the results with clinicopathological and survival data to assess the impact of CCL2 as a prognostic factor in BCa." (PMID 32429318, 2020). "The CCL2/CCR2 axis is employed to mediate the splenic recruitment of HSPCs in tumor-bearing mice." (PMID 32582203, 2020). "Indeed, CAR-T cells expressing high levels of CCR2 receptor can migrate more efficiently to tumor sites secreting CCL2 and have stronger antitumor activity." (PMID 32411789, 2020). "CCL2 has been identified as a prominent modulator in such a dynamic tumor-host interactions." (PMID 32471499, 2020). "Tumor cells are the main source of CCL-2, but it can be also secreted by non-tumor cells." (PMID 33228048, 2020). "Mice with a deficiency of either tumor necrosis factor (TNF)-α, a master proinflammatory cytokine, or C-C motif chemokine ligand 2 (CCL2), a proinflammatory chemokine, were refractory to the development of malignant tumors in the classical two-stage skin carcinogenesis model." (PMID 33322099, 2020). "Moreover, macrophage colony-stimulating factor (M-CSF) and chemokine-CC motif-Ligand2 (CCL2), present in the tumour microenvironment, facilitate interaction between HCC cells and stromal components and enhance cellular infiltration." (PMID 32466214, 2020). "Since human CCL2 could bind to murine CCR2 44, we speculate MiV may harness CCL2/CCR2 chemokine axis to track tumor cells, which is similar to donor cells." (PMID 32550891, 2020).
tumor (continued). "M-CSF induces high expression of C-C motif chemokine ligand 2 (CCL2) by macrophages, a chemokine that acts as a chemoattractant driving them to the tumor but may also affect their polarization and survival." (PMID 32656079, 2020). "CCL2 is highly expressed in tumor but also stromal cells of many cancers." (PMID 32244723, 2020). "It is speculated that CCL2 directly stimulates tumor cell proliferation, survival and migration; influences angiogenesis and acts as a chemotactic factor to tumor cells and inflammatory monocytes." (PMID 32244723, 2020). "In addition, tumor-derived CCL2 can directly act on CCR2 positive endothelial cells to increase their permeability or indirectly via increasing CXCL12 expression, which helps CXCR4 positive cancer cells to extravasate into the PMNs." (PMID 33414786, 2020). "Interestingly, IL-6, CXCL12, RANKL, CCL2, and TGFβ secreted by both tumor and bone stromal cells are well-studied cytokines that have been implicated in induction of this process." (PMID 32585812, 2020). "In the TME (tumor microenvironment), CCL2 can be produced by both cancer and stromal cells including TAMs and shows opposing pro- or antitumoral effects depending on its type and stage; however, high CCL2 expression is generally an unfavorable prognostic factor in different types of cancers." (PMID 33238581, 2020). "This calculation revealed supra-additive upregulation of many of the same cytokines/chemokines in LKB1-reconstituted tumor spheroids co-cultured with MVNs, including CCL2 and CXCL10, while there were some differences such as IL-6, which was amplified, and CCL5, which was suppressed." (PMID 33013881, 2020). "Since we observed reduction in CCL2 levels in both the tumor and sera of CD11b-modulated tumors (i.e., GB1275 treated and CD11b KI), we hypothesized that reduced CCL2 in the blood may result in reduced levels of circulating Ly6Chi monocytes." (PMID 32528880, 2020). "Chemokines secreted by tumor cells, such as CCL2 and CSF1, recruit and polarize monocytes." (PMID 32983125, 2020). "Lastly, given the importance of CCR2+ MDSC recruitment to promoting tumor growth in our studies, we assessed whether production of MCP-1/CCL2 was host derived or tumor derived by testing syngeneic tumor growth in WT vs. MCP-1KO mice." (PMID 33322474, 2020). "CDDO-Me-mediated effects on TAM IL-10 production may be both direct and indirect, as expression of CCL2 was also significantly blunted by drug treatment in both TAMs and tumor cells." (PMID 32300202, 2020). "In our experience, TME changed towards a more inflamed environment, evidenced by the increase of cytokines like CXCL10 and CCL2, and the decrease of immunosuppressive molecules (like FoxP3 and Nos2), and molecules that promote tumor growth and invasiveness (like IL10 and TGFβ)." (PMID 32064039, 2020). "Since CCL2 is important for recruiting macrophage, we questioned whether other chemokines or cytokines are involved in tumor progression." (PMID 32244522, 2020). "There is a correlation between tumor grade and expression of CCL2." (PMID 32456359, 2020). "We extended these observations to tumor biology where the muted responses toward CCL2 and CCL3 due to the loss of VISTA clearly predicted an alteration in the chemotaxis of monocytic cells to the tumor site and a change in the immune cell demography of the TME." (PMID 31803182, 2019). "The expression of CCL2 was significantly associated with the clinical stage, perineural invasion, and distant metastasis (P < 0.05), whereas not with age, gender, tumor site, and tumor histotype (P > 0.05)." (PMID 31024838, 2019). "In another setup, monocytic-cell-derived TNFα upregulated CCL2 secretion from tumor cells, which then promoted TNFα secretion from monocytic cells, thereby forming a vicious circle of cross-regulation that may contribute to tumor progression and malignancy." (PMID 31921102, 2019).
tumor (continued). "Here, we provide an overview of the pleiotropic effects of CCL2 signaling on cells of the myeloid lineage, beyond chemotaxis, and highlight how these actions might help to shape immune cell behavior and tumor immunity." (PMID 31921102, 2019). "In their publication, the authors suggested a mechanism by which CCL2 and IL-6 potentiate tumor progression, as the tumor infiltrating monocytes are protected from apoptosis (see CCL2 Enhances Myeloid Cell Survival and Proliferation) and skewed toward a protumorigenic M2 phenotype." (PMID 31921102, 2019). "However, in terms of the tumor volume ratio (%) and doubling time (DT), the CCL2-mNOX-E36 group had a significantly lower tumor volume ratio and a longer DT than those of the other two groups." (PMID 31366997, 2019). "In the lungs, alveolar and interstitial macrophages upon taking up these EVs start to secret CCL2 favoring the recruitment of iMo, which in turn differentiate into macrophages, mostly M2-like cells, promoting tumor growth by the secretion of IL-6 and deposition of fibrin." (PMID 31447834, 2019). "More evidence shows that CCL2 mediates tumor cell killing indirectly by activating macrophages." (PMID 31921102, 2019). "Moreover, CTRP1 knockdown inhibited CCL2 expression, and CCL2 overexpression reversed the inhibition of cell proliferation and migration induced by CTRP1 knockdown, suggesting that CTRP1 promoted tumor progression by regulating CCL2 expression." (PMID 31183364, 2019). "Depletion of tumor-cell-derived CCL2 also inhibited metastatic seeding." (PMID 31481958, 2019). "In human pancreatic tumor as well as murine pancreatic lesion model, the tumor microenvironment releases CCL2 and thereby actively recruits CCR2-expressing CD14+CD16− classical monocytes from bone marrow to blood stream, which is a prognostic factor of worse outcome." (PMID 31474975, 2019). "In the residual tumor, the overexpression region of CCL2 and TNFα overlapped closely." (PMID 31780645, 2019). "The crosstalk between TAMs and tumor cells enhances the CCL2 production by tumor cells." (PMID 31780645, 2019). "CCL2 is expressed by a variety of cells, such as endothelial cells, smooth muscle cells, fibroblasts, epithelial cells, mesangial cells, astrocytes, T cells and tumor cells, as well as by myeloid cells." (PMID 31921102, 2019). "Therefore, DSC perfusion MRI is a suitable in vivo modality to assess the effects of CCL2-mediated TAM recruitment on the tumor vasculature in GBM." (PMID 31366997, 2019). "Moreover, most tumor cell lines produce CCL2 and are able to grow in vivo in wild-type as well as CCL2 knockout mice." (PMID 31921102, 2019). "Tumor-derived CCL2 increases polarization of macrophages into the M2 population." (PMID 30680411, 2019). "HOTAIR regulates CCL2 expression, which may be involved in the recruitment of macrophages and MDSCs to the tumor microenvironment." (PMID 31572568, 2019). "Growing preclinical studies showed that targeting TAMs by blocking the CCL2/CCR2 axis inhibited the tumor development and might be a potential therapeutic revenue for several malignancies." (PMID 31024838, 2019). "MSC/fibroblast-derived chemokines, including murine CXCL1 and CXCL2 (counterparts of human CXCL8), CCL2 and CCL5 were associated with recruitment of neutrophils, tumor-associated macrophages and myeloid-derived suppressor cells to TNBC tumors, where they promoted disease course." (PMID 31031757, 2019). "The CCL2 is not a specific chemokine for MDSCs and is a chemoattractant for several tumor-related myeloid cells (including monocytes and tumor-associated macrophages)." (PMID 31404149, 2019). "Furthermore, during the hepatocellular carcinoma development, oncogene-induced senescent hepatocytes secrete SASP cytokines, e.g., CCL2, to exert pro-tumor effects." (PMID 31861892, 2019).